RBX1 (ring-box 1)
Diseases named in the same sentence as RBX1 in open-access papers (continued):
Sharing a sentence is not in itself a finding about the gene and the disease.
infection (7 papers, 2020 to 2025). The state of being infected such as from the introduction of a foreign agent such as serum, vaccine, antigenic substance or organism. "Western-blotted nuclear and cytoplasmic fractions of uninfected and O. tsutsugamushi infected cells were examined 72 h post infection (hpi) with Cul1, Skp1, and Rbx1 antibodies." (PMID 39976440, 2025). "For further assurance, we achieved loss of function of both Cullin3 and Rbx1 separately before checking levels of Nrf2 and HO-1 in response to RV-SA11 infection." (PMID 32322337, 2020). "CUL1 and CCNE1, two S phase target genes, whose mRNA levels were upregulated at various time points after DTMUV infection, while the mRNA levels of RBX1, SKP2 and CCNE2 were decreased at all the time points, moreover, CCNE2 was time-dependently downregulated." (PMID 32897243, 2020). "Interestingly, other NER genes involved in damage recognition, such as DDB1, CETN2, and RBX1, were found to be downregulated during the infection and, in the case of DDB1, data support a putative involvement of CagA." (PMID 33339161, 2020). "In addition to revealing the TRAF-2 and TRAF-6 ubiquitin ligase complexes, which have known roles in immune signaling during infection, this analysis identified ubiquitin ligase complexes, including CUL3, RBX1, and MDM2, that have not been previously implicated in Mtb pathogenesis." (PMID 31951200, 2020).
endocrine system disorder (1 paper, 2021). A disease involving the endocrine system. "Network 1 (IPA® score 67) was annotated to endocrine system disorders, gastrointestinal disease, and immunological disease, and identified H4 clustered histone 1 (H4C1), histone h3, and E3 ubiquitin-protein ligase (RBX1) as nodes with the highest number of network connections." (PMID 34845190, 2021).
RBX1 also shares sentences with these, for which no sentence is quoted: multiple myeloma (3 papers); esophageal cancer (2); influenza (2); 3M syndrome (1); Alzheimer disease (1); anaplastic thyroid carcinoma (1); asthma (1); autism (1); bipolar disorder (1); brain diseases (1); breast adenocarcinoma (1); cervical carcinoma (1); choroidal melanoma (1); chronic myeloid leukemia (1); endometrial cancer (1); Epstein-Barr virus infection (1); Fanconi anemia (1); gastrointestinal disease (1); gynecological tumors (1); hepatitis C (1); human papillomavirus infection (1); invasive bladder transitional cell carcinoma (1); neurodegenerative disease (1); neurodevelopmental disorder (1); ovarian tumors (1); Parkinson’s (1); primary effusion lymphoma (1); thyroid cancer (1); transitional cell carcinoma of the bladder (1); triple-negative breast carcinoma (1).
A further 2 diseases each share a sentence with RBX1 in 1 paper.